BCL2 (BCL2 apoptosis regulator)
Diseases named in the same sentence as BCL2 in open-access papers (continued):
Sharing a sentence is not in itself a finding about the gene and the disease.
gastric cancer (continued). "Also it decreased Bcl-2 (P < 0.01, P < 0.05), therefore promoting apoptosis in preventing the occurrence of gastric cancer." (PMID 28119756, 2016). "Study about the impact of convergent points or molecular switch nodes, such as B-cell lymphoma-2 (Bcl-2) family members, in deciding the fate of gastric cancer cells, may provide new clue to unmask the crosstalk between autophagy and apoptosis in oncogenesis." (PMID 26910278, 2016). "And it could downregulate antiapoptotic gene Bcl-2 and proliferative genes in gastric cancer, such as EGF and EGFR." (PMID 28119756, 2016). "In addition, miR-204 also plays important role in the sensitivity of cancer cell to chemotherapy drugs in neuroblastoma and gastric cancer through targeting BCL2." (PMID 27095441, 2016). "Moreover, BCL2 inhibitor ABT-199 induced cell death in gastric cancer cell lines, but 5-aza-dC/LPS and ABT199 cotreatment relatively decreased cell death." (PMID 26675260, 2016). "In our research, we demonstrated that CVB-D might cause apoptosis via up-regulation of the apoptosis related proteins, such as cleaved Caspase-3 and ratio of Bax/Bcl-2, in gastric cancer cells." (PMID 26610442, 2015). "Further studies showed that anti-miR-34a oligonucleotides could block the luteolin-induced Bcl-2 suppression in gastric cancer cells." (PMID 26305257, 2015). "Bcl-2 expression was predominantly present within the cytoplasm of gastric cancer cells." (PMID 25435977, 2015). "The qRT-PCR experiments were designed to detect the expression levels of the top 5 ranking HAX1, RNF2, PIM3, TPP1 and CAV1 genes in addition to the seed proteins ABCB1, AKT1 and BCL2 in both the SGC7901 gastric cancer cell line and the Adriamycin resistant SGC7901/ADR cell line." (PMID 26039373, 2015). "In addition, studies have also reported that bLf reduces the levels of intrinsic protein Bcl-2 in stomach cancer cells as well as caspase-3 cleavage in squamous cell carcinoma." (PMID 25998617, 2015). "Zhu found that CD133 may contribute to the resistance of gastric cancer cells to chemotherapy drug through P-gp, Bcl-2 and Bax, involved with PI3K/Akt signal pathway." (PMID 26503471, 2015). "Besides, loss of endogenous miRNAs repress Bcl-2 gene expression had been documented in CLL and human gastric cancer." (PMID 25006537, 2014). "According to our results, the negative expression of bcl-2 is an independent risk factor for gastric cancer recurrence." (PMID 24555747, 2014). "The objective of the current study is to determine whether bcl-2 expression can predict disease recurrence after curative resection in patients with gastric cancer." (PMID 24555747, 2014). "Concluding, the differences in the expression of the proteins in gastric cancer cells, especially Bcl-2, may indicate that they have an effect on the type of apoptotic disorders, and thus on the formation of various types of cancers." (PMID 24741635, 2014). "Our study confirmed the role of Bcl-2 in the formation of various forms of gastric cancer." (PMID 24741635, 2014). "Bcl-2 expression was positive in 21.2% of all gastric cancer tissues." (PMID 24555747, 2014).
gastric cancer (continued). "For example, miR-15b, which is down-regulated in pre-treatment high risk cases here, has previously been shown to play a role in the development of multi-drug resistance in gastric cancer cells through up-regulation of the Bcl2 protein and consequent modulation of apoptotic pathways." (PMID 23308219, 2013). "bcl-2 expression was positive in 22.2% of all gastric cancer tissues." (PMID 22216342, 2011). "The results indicated that the expression of bcl-2 could provide additional prognostic information in the patients with gastric cancer." (PMID 22216342, 2011). "The expression of bcl-2 was an independent prognostic factor for patients with gastric cancer; it might be a candidate for the gastric cancer staging system." (PMID 22216342, 2011). "We found that SPARC siRNA could induce gastric cancer cell apoptosis and simultaneously reduce the ratio of Bcl-2 to Bax." (PMID 20525171, 2010). "The present study aimed at determining whether arsenic trioxide inhibits proliferation and induces apoptosis in SGC7901 human gastric cancer cells, accompanied by conformational changes of Bcl-2 and changes in total Bcl-2 levels." (PMID 20403207, 2010). "We therefore investigated whether miR-34 restoration could sensitize gastric cancer cells with high a level of Bcl-2 to chemotherapy." (PMID 18803879, 2008). "Overexpression of Bcl-2 is observed in a majority of human cancers, including gastric cancer." (PMID 18803879, 2008). "Considering low frequency of reactivity of gastric cancer cells in many reports including that of us, it seems to be rational to perform a large scale and inter-institutional study using specific measurements as electronic measurements to verify the exact rate of bcl-2 reactivity in gastric cancer." (PMID 16759362, 2006). "But there are increasing reports on Bcl-2 reactivity in gastric cancer with much higher frequency." (PMID 16759362, 2006). "The authors reported only 2 bcl-2 positive cases out of 30 gastric carcinomas." (PMID 16759362, 2006). "Studies could show the reactivity of tumor cells in gastric carcinoma for bcl-2 with various frequencies." (PMID 16759362, 2006). "The anti-gastric cancer activity of anti-MUC1 and rosmarinic acid is reflected in the inhibition of mRNA expression of enzymes that produce cancer-associated antigens and specific antigens; the promotion of BAX, Bad and Caspase-3 and -9; and inhibition of Bcl-2 expression." (PMID 38675663, 2024). "Furthermore, in human gastric cancer cells AGS, quercetin caused morphological changes and reduced total survival through apoptotic cell death, decreased anti-apoptotic proteins Mcl-1, Bcl-2, and Bcl-x and increased the pro-apoptotic proteins Bad, Bax, and Bid." (PMID 35971151, 2022). "Furthermore, evodiamine raised the ratio of Bax/Bcl-2 in gastric cancer cells, which might lead to activate caspase-9, consequently inducing apoptosis." (PMID 36135210, 2022). "Additionally, the anticancer actions of this carotenoid were associated with autophagy and apoptosis induction through an increase in beclin-1, microtubule-associated protein 1 light chain 3, and cleaved caspase-3, and a reduction in Bcl-2 in gastric cancer cells." (PMID 34677429, 2021). "Although this study confirmed that narciclasine could inhibit the expression of Bcl-2 and promote the expression of Beclin1, whether narciclasine-mediated autophagy and apoptosis of gastric cancer cells are related to the Beclin1-Bcl-2 regulatory mode needs further verification in future studies." (PMID 34753517, 2021).
gastric cancer (continued). "Moreover, our results also showed that gastrin knockdown caused reduction of Bcl-2 levels and elevation of Bax levels in a ROS-dependent manner, indicating that gastrin knockdown promotes gastric cancer cell apoptosis by modulating the expression levels of Bax and Bcl-2." (PMID 33937399, 2021). "Therefore, BCL-2 was positively regulated by GSE1 in gastric cancer cells." (PMID 33623790, 2021). "The possible mechanisms of the components of the Zhishi-Baizhu herb pair in treating gastric cancer might be related to luteolin and naringenin, which intervened with the targets AKT1, MMP9, IL-6, CCND1, BCL2, MTOR, and MDM2, and are linked with the PI3K-Akt and IL-17 signaling pathways." (PMID 34899944, 2021). "The increased Bax/Bcl-2 ratio exerts proapoptosis function in neuroblastoma (NB) and gastric cancer (GC)." (PMID 32278350, 2020). "Consequently, Bax overexpression and Bcl-2 underexpression in gastric cancer cells may account for the inductive effect of Beclin 1 on apoptosis via mitochondrial pathway." (PMID 33425768, 2020). "The combination of RT with OXA exerted a synergistic anticancer effect, downregulated the Bcl-2/Bax ratio by activating the p38 signaling pathway, and upregulated the expression of apoptotic proteins in the caspase family to trigger apoptosis in gastric cancer cells." (PMID 31781632, 2019). "In summary, we demonstrated that expression of HOXA10 and BCL2 was significantly upregulated in gastric cancer (GC) tissues." (PMID 31364281, 2019). "To clarify whether the up-regulation of PTEN by TQ and cisplatin led to the apoptosis of gastric cancer cells via mitochondrial pathway, we detected the levels of Bcl-2, Bax, procaspase-9, procaspase-3, Cyt C, AIF, cleaved caspase-9, cleaved caspase-3 using western boltting." (PMID 29156767, 2017). "Our data suggested that the protein levels of cleaved caspase-3 and cleaved PARP, and the ratio of Bax/Bcl-2, were significantly increased after bufalin treatment, indicating that caspase and mitochondrial-mediated apoptotic pathway were involved in bufalin-induced apoptosis of gastric cancer cells." (PMID 28838965, 2017). "In addition, miR-204 could affect chemoresistance in neuroblastoma and gastric cancer cells by targeting BCL2." (PMID 26134825, 2015). "However, the value of bcl-2 in predicting gastric cancer recurrences is still unclear." (PMID 24555747, 2014). "Therefore, the regulation of Bcl-2 and Bax expression may be a key mechanism underlying SPARC induction of apoptosis in gastric cancer cells." (PMID 20525171, 2010). "The mechanism of miR-34-mediated suppression of gastric cancer cell self-renewal might be related to the direct modulation of downstream targets Bcl-2, Notch, and HMGA2, implying that miR-34 may be involved in gastric cancer stem cell self-renewal/differentiation decision-making." (PMID 18803879, 2008). "Furthermore, enhanced bcl-2 expression may be as a result of Gli-1 re-expression as confirmed in gastric carcinoma cells." (PMID 17505514, 2007). "Similar observations were reported in pancreatic and gastric cancer cells, in which 5–20 μM of SFN induced apoptosis with decreases in Bcl2 and increases in the Bax and caspase-3 levels." (PMID 40143169, 2025). "For instance, TEAD4-activated MNX1-AS1 has been shown to facilitate gastric cancer progression through the EZH2/BTG2 and miR-6785-5p/BCL2 axes." (PMID 39735666, 2025). "major compounds involved a lower Bcl-2/Bax ratio and upregulation of CASP3 and CASP9 levels, highlighting significant differences in anti-gastric cancer activity between extracts prepared from fresh versus dried P. japonicus var." (PMID 40573220, 2025). "In addition, ISO not only has a pro-apoptotic effect on human gastric cancer cells, but also shows a good pro-apoptotic effect in human melanoma cells and human bladder cancer cells, which increases the expression of Bax and caspase 3 proteins, and reduces the expression of Bcl-2 protein." (PMID 40507124, 2025).
gastric cancer (continued). "The same study revealed that inhibiting HMGB1 down-regulated Bcl-2 and MMP-2 but up-regulated Bax in gastric cancer cells." (PMID 40264171, 2025). "Western blot demonstrated Bcl‐2 downregulation alongside Bax upregulation with treatment of ABT‐627 in both NCI‐N87 and MKN‐28 gastric cancer cells." (PMID 40245183, 2025). "miR-1915-3p modulated the development of gastric cancer and colorectal cancer through the repression of RAGE, NFIX, and BCL-2." (PMID 39123189, 2024). "PPI analysis revealed five important proteins, such as ALB, BCL-2, NF-κB, HIF1A, and IL6, from 44 target proteins of gastric cancer according to statistical significance." (PMID 39816318, 2024). "Studies performed on gastric cancer cells indicate the effect of reversing the abnormal expression of proteins such as p-JAK2, p-STAT3, Bcl-2, cleaved caspase-3, cleaved PARP, and Ki67 by GAL." (PMID 38674891, 2024). "In our study, TNF, IL6, BCL2, PTEN, CTNNB1, and SRC are presented as common target genes between gastric cancer and AMK." (PMID 38612999, 2024). "After applying the compound to breast, thyroid, and gastric cancer cells, an increased level of split PARP and Bax proteins and a decreased level of Bcl-2 protein were observed." (PMID 38674891, 2024). "In gastric cancer cells, 100–400 μM UA induced G0/G1 arrest (in BGC823 cells) or G2/M (in SGC7901 cells) after 24 h treatment and apoptosis with the rise of the Bax:Bcl2 ratio (also in vivo) and caspase 3 activation as well as autophagy." (PMID 39457512, 2024). "COE reduced the expression levels of Bcl-2, Bcl-xL, and the PI3K/Akt/mTOR/p70s6k signaling pathway proteins, while simultaneously enhancing the levels of Bax and caspase proteins in gastric cancer cells." (PMID 38633608, 2024). "Albumin (ALB), B-cell lymphoma 2 (BCL-2), nuclear factor kappa B subunit 1 (NFKB1), hypoxia-inducible factor 1 alpha (HIF1A), and interleukin 6 (IL-6) had a higher expression in gastric cancer than in normal conditions." (PMID 39816318, 2024). "The results revealed that the aqueous extract of Taraxaci herba could promote the apoptosis of gastric cancer cells, reduce the migration ability of gastric cancer cells, and reduce the expression of pro-proliferation and anti-apoptosis genes (Erk, survivin and Bcl2)." (PMID 39338278, 2024). "In general, it was found that Luteolin exerted its biological properties by inhibiting Cyclin D1, Cyclin E, Bcl2, MMP-2, MMP-9, N-cadherin, Vimentin, and inducing p21, Bax, and E-Cadherin expressions in gastric cancer cells." (PMID 36992138, 2023). "The researchers also showed that, in gastric cancer, PVT1 increases 5-FU resistance by activating Bcl-2, which in turn inhibits apoptosis." (PMID 37104009, 2023). "Studies on gastric cancer cells have shown that after regulation of AKT signal pathway, the expressions of Bax and Bcl-2 proteins can be regulated and apoptosis occurs." (PMID 36249752, 2022). "Subsequently, we suppressed β-catenin and BCL2 expression in collagen cultured ITGB1 positive cells, and then examined the cytotoxicity of 5-FU to gastric cancer cells." (PMID 34319913, 2021). "BCL-2 was proved to be positively regulated by GSE1, and BCL-2 also played a promoting role in trastuzumab resistance of gastric cancer cells." (PMID 33623790, 2021). "It was determined that gracillin could fight against gastric cancer cells by inhibiting the cell proliferation participated by the PI3K/AKT pathway and cell cycle arrest, suppressing the EMT pathway-regulating cell migration, and inducing bcl2-associated mitochondrial apoptosis." (PMID 34630074, 2021). "Naringenin (MOL71) and luteolin (MOL75) regulated the expression of BCL2 and CASP3 and indirectly regulated the expression of PAPR1 to inhibit the development of gastric cancer." (PMID 34773055, 2021). "EBV has also been shown to induce chemoresistance to 5-FU in gastric cancer cells by decreasing the cleavage of PARP and caspase 3 and increasing the anti-apoptotic Bcl2 expression." (PMID 34745965, 2021).
gastric cancer (continued). "Simvastatin sensitizes gastric cancer to capecitabine in human gastric cancer xenografts by inhibiting NF-κB activation and abrogation of cyclin D1, cyclooxygenase-2 (COX-2), survivin, Bcl-2, CXC motif receptor 4, and MMP-9." (PMID 34065757, 2021). "In gastric cancer cells, overexpressing CTTN resulted in an increased percentage of apoptosis, increased pro-apoptotic marker Bax, and decreased anti-apoptotic marker Bcl-2." (PMID 34831092, 2021). "BCL-2 was a downstream gene positively regulated by GSE1 and also performed promoting the role of trastuzumab resistance in HER2-positive gastric cancer cells." (PMID 33623790, 2021). "For instance, MNX1-AS1 overexpression promotes gastric cancer progression via the EZH2/BTG2 and miR-6785-5p/BCL2 axis." (PMID 33882027, 2021). "In gastric carcinoma, overexpressing SNF5 in cells induce apoptosis by inhibiting Bcl-2 and upregulating Bax." (PMID 34876150, 2021). "Furthermore, we elucidated the mechanism of gracillin’s benefits against gastric carcinoma: that gracillin inhibits cell proliferation involving the PI3K/AKT pathway and cell cycle arrest, suppresses the EMT pathway to regulate cell migration, and induces bcl2-associated mitochondrial apoptosis." (PMID 34630074, 2021). "Beclin 1 down-regulated the expression of VEGF, E-cadherin, Bcl-2, but up-regulated the expression of LC-3B, NF-κB, PI3K, Akt1/2/3 and MDR in xenograft tumor of gastric cancer cells." (PMID 33425768, 2020). "The interference with HOTAIR can decrease the expression of Wnt and β-catenin, thereby increasing the BAX/BCL-2 ratio, activating caspase-3, promoting apoptosis, and reversing DDP resistance in gastric cancer cells in vitro and in vivo." (PMID 32460771, 2020). "Further mechanism study has revealed that SNHG5 down-regulates BAX expression and up-regulates BCL-2 expression, thereby inhibiting apoptosis and promoting DDP resistance of gastric cancer cells." (PMID 32460771, 2020). "We probed these mechanisms in gastric cancer cells and show that Celastrol induces phosphorylation of JNK and decreases Bcl-2:Bax ratios in both cell lines." (PMID 32929349, 2020). "LncRNA SNHG5 reduced DDP sensitivity of BGC823 and SGC7901 gastric cancer cells through up-regulating expression of MDR1, MRP1 and Bax as well as downregulating Bcl-2 expression." (PMID 32192494, 2020). "To validate their relationship in gastric cancer cells, we used FAK inhibitor to block its function and the effects of Rab11a on cyclin D1, MMP2, and Bcl-2 were significantly reduced." (PMID 33178272, 2020). "Curcumin inhibits Bcl-2, Bcl-XL, VEGF, c-Myc, ICAM-1, EGFR, STAT3 phosphorylation, and cyclin D1 genes involved in the various stages of breast, prostate, and gastric cancer proliferation, angiogenesis, invasion, and metastasis." (PMID 33178666, 2020). "TSLL inhibited the proliferation of gastric carcinoma cells by decreasing PCNA levels, and induced apoptosis by up-regulating the expression of Bax and down-regulating the expression of Bcl-2." (PMID 32368309, 2020). "A recent study reported that TRX potentiates 5-fluorouracil treatment in human gastric cancer by suppressing the STAT3/NF-κB and Bcl-2 signaling pathways." (PMID 31182097, 2019). "In summary, the antitumor effect of gramicidin on gastric cancer cells was preliminarily explored, in which gramicidin may inhibit cell proliferation and induce G2/M cell cycle block by down-regulating the FoxO1 and cyclinD1 while down-regulating tumor suppressor genes Bcl-2 to induce apoptosis." (PMID 31767027, 2019). "Crocin also exhibited cytotoxicity against human gastric cancer AGS cells by apoptosis induction through increasing caspase activation and Bax/Bcl-2 ratio." (PMID 31354479, 2019). "For examples, PAB inhibits mitochondria-mediated apoptosis pathways in human gastric carcinoma BGC-823 and MKN-45 cells and cervical cancer HeLa cells through the modification of the ratio of Bax/Bcl-2." (PMID 31623058, 2019).